KHSRP (KH-type splicing regulatory protein)
Diseases named in the same sentence as KHSRP in open-access papers (continued):
Sharing a sentence is not in itself a finding about the gene and the disease.
ZIKV infection (1 paper, 2023). "Like hBMECs, hSerCs showed no alteration in HuR, KHSRP, or AUF1 expression following ZIKV infection." (PMID 37707056, 2023). "We found that AUF1, HuR, and KHSRP were expressed constitutively in mock and ZIKV-infected hBMECs, with no change in expression following ZIKV infection." (PMID 37707056, 2023).
tumor (35 papers, 2011 to 2025). "Increased KHSRP expression was significantly associated with advanced tumor stages as well as lymph node and distant metastasis." (PMID 31775888, 2019). "However, venous invasion (v) and the depth of tumor invasion (pT) tended to be associated with cytoplasmic and nuclear KHSRP immunoreactivities." (PMID 29254151, 2017). "The results showed that both KHSRP knockdown and carboplatin treatment significantly suppressed tumor growth, as evidenced by reduced tumor volume and weight." (PMID 41194272, 2025). "Several studies have investigated KHSRP’s role in tumorigenesis and cancer progression, revealing its diverse functions across different tumor types." (PMID 39866240, 2025). "For example, KHSRP has been shown to downregulate the mRNAs of tumor suppressors, thereby promoting tumor growth and proliferation." (PMID 39866240, 2025). "In contrast, KHSRP overexpression reduced carboplatin-induced cell apoptosis in tumor tissues when compared to the NC + carboplatin group." (PMID 41194272, 2025). "KHSRP plays a critical role in cancer biology, impacting various aspects of tumor progression, metastasis, and treatment resistance." (PMID 39866240, 2025). "Conversely, KHSRP overexpression mitigated the tumor-suppressive effects of carboplatin when compared to the NC + carboplatin group." (PMID 41194272, 2025). "In a mouse xenograft model, we further observed a significant reduction in tumor volume in the KHSRP-silenced group." (PMID 39866240, 2025). "In vivo, KHSRP silencing led to a significant reduction in tumor volume and increased immune cell infiltration in the mouse xenograft model." (PMID 39866240, 2025). "Thus, we suspected that deficiency of KHSRP may suppress tumor progression and enhance the sensitivity of NSCLC cells to carboplatin by inhibiting EMT through downregulation of HMGB1 expression; whereas the precise underlying mechanisms require further investigation in future studies." (PMID 41194272, 2025). "Meanwhile, in vivo experiments demonstrated that downregulation of KHSRP potentiated the inhibitory effect of carboplatin on tumor growth in tumor-bearing nude mice." (PMID 41194272, 2025). "H&E staining of tumor sections showed that combined KHSRP knockdown and carboplatin treatment markedly increased tumor necrotic areas compared to either sh-KHSRP-2 or NC + carboplatin treatment groups." (PMID 41194272, 2025). "Recent research has underscored the role of KHSRP in cancer, indicating its potential influence on tumor progression, metastasis, and treatment resistance." (PMID 39866240, 2025). "As expected, the combination of KHSRP knockdown and carboplatin treatment further reduced tumor volume and weight compared to either treatment alone." (PMID 41194272, 2025). "Here, we report that KHSRP acetylation, a new post‐translational modification of KHSRP, is tightly associated with AR activity and DDR regulation, which serves tumor growth and malignancy by impairing DDR‐related mRNA decay in PCa." (PMID 38501452, 2024). "To further investigate how KHSRP modulate the pro-tumor features of MDA-MB-231 cells, we performed whole transcriptome sequencing (RNA-seq) experiment for siKHSRP and NC samples." (PMID 38926398, 2024). "This study found that androgen can significantly induce acetylation of KHSRP, which intrinsically drives tumor growth in xenografted mice." (PMID 38501452, 2024). "In conclusion, KHSRP knockdown arrested tumor cell metastasis perhaps by promoting the cilium function." (PMID 38926398, 2024). "In conclusion, the diverse functions of KHSRP in different tumors indicate that its role in cancer progression and drug sensitivity is highly dependent on the tumor cell type." (PMID 39439895, 2024). "The protein level of KHSRP was further assessed by using the data from clinical proteomic tumor analysis consortium (CPTAC) group." (PMID 38926398, 2024).
tumor (continued). "The silico analysis indicated that KHSRP knockdown increased cytotoxic cell infiltration in the tumor microenvironment to potentiate anti-tumor effects." (PMID 39439895, 2024). "By classifying TCGA samples into normal and primary tumor groups, we found that KHSRP expression was significantly increased in primary tumor samples." (PMID 38926398, 2024). "KHSRP expression was elevated in the tumor tissues based on the matched analysis (p < 0.05), but not the comparative analysis." (PMID 39439895, 2024). "Depletion of the MLXIPe/KHSRP/PSMD9 regulatory complex inhibited tumor growth and RT sensitization of bone mPCa xenograft in vitro and in vivo." (PMID 36632223, 2023). "Such as LncRNA AB074169 functions as a tumour suppressor during PTC tumorigenesis via modulation of KHSRP‐mediated CDKN1a expression." (PMID 34337858, 2021). "Increased KHSRP and HNRNPC expression was significantly associated with advanced tumor stages and metastasis (both lymph node and distant)." (PMID 31775888, 2019). "The results showed that DU145-shKHSRP cells displayed a sharper curve in cell index and a higher slope value of migration compared to that of DU145-shRNA-Ctrl cells, which indicated that KHSRP suppressed tumor cell migration." (PMID 29020972, 2017). "Among these miRNAs, the let-7 family, which are important tumor suppressor miRNAs, are the most classic examples of KHSRP positively regulating miRNA biogenesis." (PMID 29020972, 2017). "The abilities of soft-agar colony formation, migration, invasion and xenografted tumor growth were increased when KHSRP stably knockdown in DU145 cells, which was attributed to downregulation of TL-G-Rich miRNAs." (PMID 29020972, 2017). "Overexpression of KHSRP in tumor cells, particularly in the cytoplasm, was an independent prognosticator for overall survival." (PMID 29254151, 2017). "The overall role of KHSRP in carcinogenesis has been controversial, because KHSRP exerts oncogenic or tumor suppressive functions through various mechanisms in different cancer types." (PMID 29254151, 2017). "KHSRP mainly enhances tumor cell migration and invasion by promoting the maturation of miR-130b, miR-21 and miR-301a and by indirectly inhibiting the expression of their targets, such as endogenous EMT inhibitors BMP6, PDCD4 and TIMP3." (PMID 29254151, 2017). "Further study showed that three of the genes, FLNA, KHSRP and HCFC1, also functioned in vivo, and knocking them down caused multifocal tumor in a mouse model." (PMID 23593504, 2013). "Additionally, A549 cell xenografts were established in nude mice to investigate the tumor growth-promoting effects of KHSRP in vivo." (PMID 41194272, 2025). "Moreover, the tumor sphere formation assay showed that the downregulation of KHSRP markedly reduced both tumor-sphere formation ability and stemness." (PMID 39866240, 2025). "KHSRP may also contribute to the maintenance of CSCs, which are thought to drive tumor initiation, therapy resistance, and recurrence." (PMID 39866240, 2025). "Additionally, TUNEL assay results suggested that the combination of KHSRP knockdown and carboplatin treatment significantly increased cell apoptosis in tumor tissues relative to single treatments." (PMID 41194272, 2025). "Inhibiting KHSRP function could restore the expression of tumor suppressor genes, reduce epithelial-mesenchymal transition (EMT) and metastasis, and sensitize cancer cells to chemotherapy." (PMID 39866240, 2025). "In non-small cell lung cancer (NSCLC), higher levels of KHSRP are associated with longer patient survival and reduced cell migration and metastasis, suggesting that KHSRP may play a tumor-suppressive role in this context." (PMID 39866240, 2025). "Furthermore, KHSRP knockdown increased the infiltration of cytotoxic cells within the tumor microenvironment, thereby enhancing the anti-tumor effect." (PMID 39439895, 2024).
tumor (continued). "Additionally, the KHSRP protein level in subcutaneous tumours in the UGS NPs group was also found to be significantly reduced." (PMID 39439895, 2024). "However, we find that the aberrant acetylation of KHSRP is the authentic and intrinsic driver for tumor growth in PCa, which is also confirmed in PCa patient samples according to the Gleason Score." (PMID 38501452, 2024). "All the results confirmed that KHSRP as the oncogene, participated in the pRCC tumor progression." (PMID 39439895, 2024). "Therefore, our data demonstrate that high KHSRP expression enhanced tumor growth and metastasis in vivo, which was consistent with our in vitro findings." (PMID 31775888, 2019). "To evaluate whether KHSRP could promote tumor metastatic capacity in vivo, we injected A549-NC and A549-shKHSRP cells into the lateral tail veins of nude mice (eight mice per group)." (PMID 31775888, 2019). "This suggested that KHSRP plays a key role in tumor-suppression." (PMID 29020972, 2017). "In order to assess whether SUMOylation of KHSRP influences the migration capacity of tumor cells, we performed a RTCA-migration assay." (PMID 29020972, 2017). "Moreover, to investigate whether KHSRP SUMOylation affects xenograft tumor growth in vivo, DU145 stable cell lines were inoculated subcutaneously into the backs of nude mice." (PMID 29020972, 2017). "Thus, tumor cells with high levels of KHSRP, might have a reduced capacity to survive genotoxic therapies due to defective G1 checkpoints." (PMID 25993413, 2015). "KHSRP overexpression promoted the proliferation and migration of NSCLC cells in vitro, as well as the tumor growth in vivo." (PMID 41194272, 2025). "Our study found that KHSRP acetylation as a downstream regulator of AR can widely promote the expression of DDR‐related genes, especially the AREs‐containing genes, to drive tumor growth in PCa." (PMID 38501452, 2024). "More importantly, our investigation reveals that high expression levels of KHSRP and HNRNPC are significantly correlated with tumor metastasis and serve as independent prognostic factors for the poor outcomes of NSCLC patients." (PMID 31775888, 2019). "Furthermore, compared to single treatments, the combination of carboplatin and KHSRP knockdown further reduced KHSRP, HMGB1, N-cadherin, vimentin, and Ki67 levels, and increased E-cadherin levels in mouse tumor tissues." (PMID 41194272, 2025). "More intriguingly, the KHSRP mRNA expression was related to neither the clinical tumor stages of PCa nor the patient's overall survival." (PMID 38501452, 2024). "Ebv-circLMP2A interacted with KHSRP to increase the KHSRP-mediated degradation of VHL mRNA, resulting in an accumulation of HIF1 under hypoxia, which was crucial in controlling tumor angiogenesis in EBVaGC and might be a good therapeutic target for EBVaGC." (PMID 36386850, 2022). "After 25 days, the tumor volume of the KHSRP interference group was smaller than that of the negative control group (P < 0.01), and the tumor volume of the KHSRP overexpression group was significantly larger than that of the control group (P < 0.01)." (PMID 31775888, 2019). "We elucidated that KHSRP could interact with HNRNPC and HNRNPC-mediated tumor growth and metastasis could be, at least partly, attributed to the activation of IFN-α-JAK-p-STAT1 signaling pathway, which is critical for tumorigenesis and metastasis in NSCLC." (PMID 31775888, 2019). "Compared with KHSRP-WT, re-expression of KHSRP-K87R into stable cell line DU145-shKHSRP, a subset of miRNAs such as let-7 family were upregulated and consequently the tumor-suppressive capabilities were enhanced." (PMID 29020972, 2017). "Since KHSRP acetylation can respond to androgen stimuli or AR activity, we believe that KHSRP acetylation may play a critical regulatory role in the AR‐mediated DDR and is required for tumor growth in PCa." (PMID 38501452, 2024).
tumor (continued). "Also, FBP2 (KHSRP in MetaCore), a member of the single-stranded DNA-binding protein family, is a furoxan-affected RBP that was found overexpressed in different cancers and that, depending on the tumor cell type, is involved in cell proliferation, migration, and drug resistance." (PMID 37570694, 2023). "Interestingly, IF analyses, as well as ChIP assays, fully recapitulated what was previously observed in BJ‐EHLT cells, indicating that the ability of KHSRP to bind the G4 structures located within the promoter regions of c‐KIT and c‐MYC is a generalizable phenomenon, independent of tumor histotype." (PMID 39763191, 2025).
cancer (30 papers, 2013 to 2025). A tumor composed of atypical neoplastic, often pleomorphic cells that invade other tissues. "Given its diverse functions, altered KHSRP expression has been associated with various human diseases, including cancer, cardiovascular diseases, and neurological disorders, underscoring its clinical relevance." (PMID 39763191, 2025). "Quaking I-5 (QKI-5), RALY heterogeneous nuclear ribonucleoprotein (RALY), and KH-type splicing regulatory protein (KHSRP) promote cancer cell proliferation and invasion, and they are associated with OS probability in NSCLC." (PMID 36118863, 2022). "KHSRP is also a very important component of the Drosha/DGCR8 complex, and here we for the first time found that KHSRP SUMOylation was also linked to tumorigenesis and cancer progression." (PMID 29020972, 2017). "Among these miRNAs, the KHSRP knockdown-induced down-regulation was successfully validated with five cancer-associated miRNAs in three ESCC cell lines." (PMID 29254151, 2017). "KHSRP has been associated with chemotherapy resistance in certain cancers." (PMID 39866240, 2025). "To further exclude the variation of KHSRP acetylation level caused by the overall KHSRP expression, we screened the samples with a similar term of KHSRP (The difference of KHSRP intensity score between cancer and non‐cancer samples ≤ 1/3)." (PMID 38501452, 2024). "Despite its roles in different cancers, the association between KHSRP and pRCC, including its function, molecular mechanism, and clinical potential, remains unclear." (PMID 39439895, 2024). "KHSRP deficiency can cause multiple physiological abnormalities and even cancer disease." (PMID 38501452, 2024). "Some of these have been reported to exert cancer-associated functions, indicating that deregulation of KHSRP-miRNA interplay may, at least in part, affect the ESCC-specific miRNA expression profile." (PMID 29254151, 2017). "Furthermore, we observed that the dysregulation of TL-G-Rich miRNAs such as the members of let-7 family mediated by KHSRP SUMOylation was linked to tumorigenesis and cancer progression." (PMID 29020972, 2017). "KHSRP knockdown also inhibited the maturation of cancer-associated miRNAs, such as miR-21, miR-130b, and miR-301, and induced the expression of their target mRNAs, such as BMP6, PDCD4, and TIMP3, resulting in the inhibition of epithelial-to-mesenchymal transition." (PMID 29254151, 2017). "By modulating the expression of genes involved in drug metabolism, DNA repair, and apoptosis, KHSRP can enhance the resistance of cancer cells to chemotherapy, contributing to treatment failure." (PMID 39866240, 2025). "Given its involvement in multiple cancer-related processes, KHSRP is being investigated as a potential therapeutic target." (PMID 39866240, 2025). "Its diverse functions in RNA metabolism position it as a potential target for novel cancer therapies, particularly in tumors where KHSRP expression is dysregulated." (PMID 39866240, 2025). "KH-type splicing regulatory protein (KHSRP) plays an important role in cancer invasion, but the relevant mechanism is not well known." (PMID 31775888, 2019). "To further explore the role of KHSRP and HNRNPC in predicting cancer prognosis, we analyzed the KHSRP and HNRNPC mRNA expression and the corresponding clinical data from the publicly available GEO database (GSE30219, n = 293; GSE102287, n = 34)." (PMID 31775888, 2019). "Our data demonstrate how the miRNA biogenesis pathway is connected to tumorigenesis and cancer progression through the reversible SUMO1 modification of KHSRP." (PMID 29020972, 2017). "Taken together, these data demonstrate that SUMOylation of KHSRP promotes tumorigenesis and cancer progression." (PMID 29020972, 2017). "Genes regulated by KHSRP were previously thought to be involved in cell proliferation, stress response, and cancer." (PMID 23593504, 2013).
cancer (continued). "TCGA data analysis revealed that KHSRP expression is associated with the activation of pathways including Activation of ATR In Response To Replication, Transport of Mature mRNAs Derived From Intronless Transcripts, and Signaling by Wnt in Cancer." (PMID 39866240, 2025). "The intensity score of KHSRP acetylation in these samples showed that KHSRP acetylation in cancer tissues is higher than that in non‐cancer tissues, indicating that KHSRP acetylation may promote the tumorigenesis of PCa." (PMID 38501452, 2024). "Accumulating studies demonstrated that KHSRP plays an essential role in the regulation of cancers." (PMID 33638945, 2021). "Given the multifunctional property in cancers, KHSRP and KHSRP-associated networks would be a promising target for developing the treatment of cancers, such as the decoupling interaction between KHSRP and non-coding RNAs." (PMID 33638945, 2021). "It seems that KHSRP plays different roles in the metastasis and invasion of distinct cancers." (PMID 31775888, 2019). "Since our above data have proven that KHSRP SUMOylation could be regulated by hypoxia and growth factors, we questioned whether K87-SUMOylation of KHSRP is involved in tumorigenesis and cancer progression." (PMID 29020972, 2017). "Additionally, validation of these findings in cancer cells and preclinical in vivo models highlighted their biological relevance, suggesting that KHSRP may play a significant role in cancer formation and progression." (PMID 39763191, 2025). "However, the function of KHSRP seems to vary in different cancers, and the roles and mechanisms of KHSRP in the tumorigenesis of ESCC remain completely unknown." (PMID 29254151, 2017). "However, very few reports have described KHSRP function in the context of human carcinomas." (PMID 29254151, 2017). "However, some studies suggest that KHSRP may exert an opposing role in cancer." (PMID 41194272, 2025). "We thus conducted an RNA deep sequencing and showed that SB-T-101141 treatment impaired the cancer-related pathways, especially the MAPK pathway, suggesting the crucial and complicated roles of KHSRP in SB-T-101141-induced cell death." (PMID 40389408, 2025). "The biological relevancy between KHSRP acetylation and DDR was addressed further to understand the AR‐regulated DDR in this cancer disease." (PMID 38501452, 2024). "For instance, as mentioned in the introduction, KHSRP interacts with hnRNPA1, a protein known to resolve G4 structures at telomeres and in the promoters of genes such as KRAS and TRA2B, thereby modulating their transcription in cancer cells." (PMID 39763191, 2025). "It revealed that KHSRP is likely part of a post-transcriptional regulatory network that involves several ARE-BPs, possibly establishing a new component for modulation of CP drug sensitivity in cancer cells." (PMID 31522610, 2020). "The immunohistochemistry (IHC) results showed that KHSRP, SRSF3 and RBM9 were located in nucleus, and the expression of SRSF3 and RBM9 were significantly lower in cancer than normal thyroid, while there was no significantly different between KHSRP, NOVA2 and PTBP2 in carcinoma and normal tissues." (PMID 34722250, 2021).